MPO (myeloperoxidase)
Diseases named in the same sentence as MPO in open-access papers (continued):
Sharing a sentence is not in itself a finding about the gene and the disease.
cancer (continued). "Ceruloplasmin could indirectly interact with cancer cells through a shared affinity with albumin for myeloperoxidase, followed by albumin binding FcRn receptors on cancer cells." (PMID 36546919, 2022). "Given these contradictory reports, we were more concerned about the role of MPO in cancer." (PMID 35912260, 2022). "Furthermore, the levels of H3Cit-DNA complexes, MPO-DNA complexes and NE all correlated with CRP, indicating that NETs are associated with inflammation also in cancer patients." (PMID 35309730, 2022). "The identification of MPO for the specific monitoring of cardiotoxic mechanisms in cancer therapy may further enhance the detection of cancer-therapy-related cardiotoxicity." (PMID 36551214, 2022). "However, as novel biomarkers, the roles of galectin-3 and MPO in the monitoring of cancer-therapy-related cardiotoxicity remain controversial." (PMID 36551214, 2022). "Therefore, for the meta-analysis, five and four articles were considered to assess changes in gal-3 and MPO levels, respectively, before and after the cancer treatment." (PMID 36551214, 2022). "Hence, a meta-analysis was performed to assess the monitoring value of galectin-3 and MPO in cancer-therapy-related cardiotoxicity." (PMID 36551214, 2022). "In addition, macrophages and myeloid-derived suppressor cells accumulating in cancer patients express high levels of the enzyme MPO, a candidate enzyme that oxidatively modifies HDL, thereby reducing its cholesterol efflux capacity." (PMID 35577388, 2022). "Interestingly, in the recurrent cancer biopsies of our cohort, there was a significant correlation with CD66b, IL-17, MPO, and CXCR4, suggesting a stronger immune response in samples with high CD16." (PMID 34830938, 2021). "The serum MPO levels of breast cancer patients treated with doxorubicin and paclitaxel followed by trastuzumab were significantly higher than baseline values 3 months after the start of cancer treatment, and gradually decreased over the next 15 months." (PMID 34859069, 2021). "NET components, such as myeloperoxidase or histones, have been shown to directly kill cancer cells." (PMID 34503307, 2021). "The double-edged sword of MPO activity enhances innate immunity in the process of cancer cell elimination, but simultaneously imposes mutagenic potential and disrupts the extracellular space, allowing tumors to infiltrate their surroundings and metastasize more rapidly." (PMID 33916434, 2021). "The only available markers of NET formation are H3Cit and MPO-DNA, which may have prognostic value in cancer patients." (PMID 33042107, 2020). "Furthermore, H3Cit in plasma of cancer patients does correlate with NE, MPO, IL-6, and IL-8, all activators of NETosis." (PMID 33042107, 2020). "Moreover, the presence of plasma H3Cit in cancer patients strongly correlated with neutrophil activation markers neutrophil elastase (NE) and myeloperoxidase (MPO), and the inflammatory cytokines interleukin-6 and -8, known to induce NETosis." (PMID 29324871, 2018). "The modulation of the vanins–MPO axis may be effective and useful for the prevention of cancer and of inflammatory diseases of the colon." (PMID 28448444, 2017). "Some previous groups have indicated that the cancer risk, perhaps caused by a higher tendency of relapses and thus higher cumulative immunosuppressive drug doses, is higher in C-ANCA/PR3-ANCA than in P-ANCA/MPO-ANCA positive patients." (PMID 29403663, 2017). "This analysis did not report a significant association between these cancers and MPO-463G > A polymorphism, but suggested a moderately protective effect on cancer risk in Europeans." (PMID 28764808, 2017). "Neither for dichotomized MPO density in primary, nor in recurrent cancer biopsies a significant association with any clinicopathological feature was found." (PMID 27531373, 2016).
cancer (continued). "Specifically, neutrophils contain multiple enzymes such as, myeloperoxidase, interleukin-6 (IL-6), defensins, lysozyme and collagenase which may directly promote cancer cell intravasation and extravasation." (PMID 26544968, 2015). "A growing number of studies have suggested prognostic value of MPO in the setting of cancer." (PMID 25666092, 2015). "Therefore, the addition of HCQ as an MPO inhibitor fills a significant need in cancer care." (PMID 40797324, 2025). "Additionally, the analysis of TCGA database, Lee Bladder Cohort and BLAVERI bladder Cohort from the Oncomine database indicated that higher levels of MPO expression was correlated with shortened OS; this was also corroborated for various types of cancer in TCGA database." (PMID 36670069, 2023). "Circulating NET markers, including H3Cit and MPO-dsDNA, although not specific for cancer-associated NET formation, might be useful to detect relevant NETosis and thus high risk of metastasis." (PMID 36050539, 2023). "Thus, MPO levels are more sensitive to cancer treatment than TnI and NT-proBNP levels." (PMID 36551214, 2022). "However, MPO itself functions as a modulator of cancer development in multiple steps as well." (PMID 35885618, 2022). "Therefore, MPO is a potential biomarker of cancer-therapy-related cardiotoxicity." (PMID 36551214, 2022). "Interestingly, cancer patients displayed positive correlations between plasma levels of H3Cit, cfDNA, markers of neutrophil activation, and MPO-DNA complexes, suggesting that the presence of circulating H3Cit may be linked to neutrophil activation and NETs." (PMID 29324871, 2018). "While it has been suggested that there might be a relationship between MPO deficiency and cancer risk, a different publication has reported no increase in the incidence of cancer in individuals with MPO deficiency." (PMID 26719776, 2015). "Adding to the evidence for the role of NETs in cancer progression, neutrophil and NET markers like MPO and H3Cit have been detected in metastatic lesions of breast cancer patients, suggesting a potential role in metastasis." (PMID 40801632, 2025). "There is a lack of systematic in silico studies, including computational assessments (e.g., CNS MPO score), and comparative research on BBB and blood–cancer barrier penetration." (PMID 40286187, 2025). "Developing strategies that emulate the killing mechanism of neutrophils, which involves the enzymatic cascade of superoxide dismutase (SOD) and myeloperoxidase (MPO), shows potential as a viable approach for cancer therapy." (PMID 38388471, 2024). "The relationship between various types of cancer and Soluble P Selectin, NET, and MPO levels is currently still being developed." (PMID 39810847, 2024). "For instance, genes like SLC24A3, GALM, MPO, and ATP1B1 appear to be commonly down-regulated across various solid cancers, while other MRGs are frequently up-regulated in many cancer types." (PMID 38995414, 2024). "Emulating the killing function of neutrophils, which involves the enzymatic cascade of superoxide dismutase (SOD) and myeloperoxidase (MPO), is promising for cancer therapy, but developing SOD-MPO cascade in one nanozyme is challenging." (PMID 38388471, 2024). "When 3-IAA and MPO are present in high concentrations during FIRINOX treatment, the accumulation of ROS increases and the stress adaptation of cancer cells is impaired, which ultimately results in the reduced proliferation of PDAC cells." (PMID 36813961, 2023). "Further studies should include other MPO inhibitors, such as verdiperstat and AZD5904 to confirm the involvement of the enzyme activity in altering cancer cell function, both in vitro and in vivo." (PMID 37627581, 2023). "In cancer patients, NET markers such as extracellular DNA, myeloperoxidase (MPO), citrullinated histones, and NE are elevated and correlate positively with the incidence of VTEs." (PMID 37520562, 2023).
cancer (continued). "The observed decreases in these BMs with anthracycline exposure suggest that some patients with cancer have elevated MPO and CASP-1 levels at baseline because of the systemic inflammation related to cancer." (PMID 37106424, 2023). "There have been initial preclinical reports on the role of selective MPO inhibitors, verdiperstat and AZD5904 in supporting the effects of cancer immunotherapy." (PMID 37513924, 2023). "The importance of murine neutrophil MPO has been shown using a novel tripeptide MPO inhibitor [N-acetyl lysyltyrosylcysteine amide (KYC)], which diminished lung tumor burden, suggesting that targeting neutrophil MPO is a novel cancer treatment." (PMID 35784290, 2022). "Further, we elaborate on Myeloperoxidase (MPO) in the complex context of cardiovascular disease, innate and autoimmune response, development and progression of cancer and neurodegenerative diseases." (PMID 33916434, 2021). "Proteases such as NE (neutrophil elastase), MPO, bactericidal cationic polypeptides, and other NET-adsorbed moieties have been described regarding their effect on cancer and immune cells." (PMID 34899751, 2021). "Tyrosine modified by ROS and RNS can serve as a stable oxidative stress marker, a prognostic marker in cancer, and as an indicator of NOS2, MPO, or EPO activity and therefore a marker of inflammatory leukocyte-mediated tissue damage." (PMID 33167555, 2020). "Some of the differently expressed proteins were significantly expressed in the groups EA/Ctrl, AIS/Ctrl, and AIS/EA, including myeloperoxidase and APOA1, which are involved in the development of cancer." (PMID 33194326, 2020). "With regard to the density of immune cells around cancer cells on c-TMA cores, we noted a considerable variation from low density (“cold”) to high density (“hot”) for CD3, CD4, CD8, CD20, CD68, and MPO positive cells." (PMID 31817531, 2019). "The results of this review show that açaí acts in the inflammatory processes involved in induced-cancer in animals by decreasing the levels of IL-1β, IL-5, IL-6, IL-8, COX-2, TNF-α and MPO and increasing the levels of IFN-γ." (PMID 29966007, 2018). "Thus, a modulation of MPO activity may be the successful strategy for cancer prevention." (PMID 28448444, 2017). "Both MPO and ELA appeared to contribute to tissue and extracellular matrix degradation, enhancing cancer development by destroying natural barriers against metastasis." (PMID 23176085, 2012). "However, the frequency of cancer was similar between patients with GPA and MPA, as well as c-ANCA/PR3 ( +) and p-ANCA/MPO ( +) patients in our study." (PMID 40332571, 2025). "Our analysis revealed that VISTA is predominantly expressed by macrophages (CD68 +) and neutrophils (MPO +), while cancer cells (CK11 +) and fibroblasts (αSMA +) showed lower to no expression of VISTA." (PMID 40316725, 2025). "Additionally, by secreting IL-8, TNF-α, and myeloperoxidase (MPO), N2 TANs can activate macrophages and establish the TAN–TAM axis, which has been observed in several cancer types." (PMID 40805183, 2025). "This is the first study to prospectively evaluate the clinical value of novel biomarkers (IL-6, MPO, TNF-alpha) in cancer patients as potential biomarkers of cancer therapy-related cardiac dysfunction, defined according to current ESC cardio-oncology guidelines." (PMID 40362309, 2025). "The neutrophil degranulation complex was defined by the terms antimicrobial peptides (R-HAS-6803157), neutrophil degranulation (R-HSA-6798695), response to yeast (GO:0001878), and transcriptional misregulation in cancer (KEGG:05202); it included the proteins ELANE, H3-5, MPO, LYZ, and PRTN3." (PMID 39997396, 2025). "As far as we know, the CUBN/MPO ratio has never been previously studied as a promising biomarker or prognostic factor for urinary cancer or any other type of cancer." (PMID 38530585, 2024).
cancer (continued). "ANCA serology (ELISA) differed between groups (PR3 and negative ANCA) and was more prevalent in patients with cancer, whereas MPO ANCA was more prevalent in patients without cancer." (PMID 38553624, 2024). "This study found that both Soluble P Selectin, Neutrophil Extracellular Traps, NET, MPO, and confounding variables such as gender, type of chemotherapy, and type of cancer did not have a significant impact on the incidence of DVT (p > 0.05)." (PMID 39810847, 2024). "The two key biomarkers we found (i.e., MPO and PDL1) are parts of important pathways in cancer immunotherapies providing an opportunity for future studies of data science approaches for biomarkers involved in cancer." (PMID 36969221, 2023). "The present meta-analysis reveals that MPO is a useful biomarker for the early detection of cancer-therapy-related cardiotoxicity, whereas galectin-3 is not." (PMID 36551214, 2022). "NETs are composed of nuclear DNA in a web-like structures extruded from neutrophils and mixed with granular and some cytoplasmic constituents, such as neutrophil elastase (NE), myeloperoxidase (MPO), and citrullinated histone H3 (citH3), in response to infections or cancer burden." (PMID 35449078, 2022). "In the following sections we will discuss the emerging non-canonical functions of MPO, including regulating neutrophil trafficking, signaling, interactions with other immune cells and its role in inflammatory diseases and cancer." (PMID 36293108, 2022). "Based on the results from KEGG enrichment analysis, we speculated that MPO may play a role in LUAD and LUSC patients through transcriptional misregulation in cancer pathways." (PMID 35227278, 2022). "We observed a marked and progressive raise in both MPO (+150%; P < .01, +372; P < .001 and +706%; P < .001) and MDA levels (+263%; P < .01; +516%; P < .001 and +988%; P < .001) in peritumoral, UC and cancer specimens vs controls." (PMID 32022398, 2020). "Additionally, in the presented study, decreased urinary levels of a myeloperoxidase (MPO)- derived peptide were detected in urine of cancer patients, in comparison to the non-cancer controls." (PMID 29588543, 2018). "The correlation between H3Cit and MPO-DNA complexes, however, remained significant in severely ill patients without known cancer." (PMID 29324871, 2018). "There was no chemoresistant patient in the subgroup of MPO + IL-17+, neither in primary nor in recurrent cancer biopsies." (PMID 27531373, 2016). "In a multivariate cox regression analysis including age, residual disease, FIGO classification, number of chemotherapy cycles and categorized MPO and IL-17 cell density, the combination of the immune markers was an independent prognostic factor for RFS in primary cancer biopsies." (PMID 27531373, 2016). "Serum MPO concentration was not related to total mortality, respiratory mortality, or deaths from malignancies." (PMID 23637811, 2013). "Myeloperoxidase (MPO), which is abundantly expressed in neutrophils and to a lesser extent in monocytes and certain type of macrophages, has been strongly correlated with different types of cancer progression due to its role in ROS generation." (PMID 23176085, 2012). "Pure genomic DNA did not induce significant cancer cell death, supporting previous evidence that NETs’ cytotoxicity depends on the combined action of DNA scaffolding and attached granular proteins such as neutrophil elastase, myeloperoxidase, and histones." (PMID 40927723, 2025). "Although MPO level is elevated in pro-coagulant states, such as in cancer and pregnancy, its gene expression may not necessarily be increased, since this enzyme may be obtained from degranulation of leukocytes and is present in NETs." (PMID 40487734, 2025).
cancer (continued). "Caspase-3 plays a key role in the control of apoptosis, mediating cellular autophagy by participating in a cascade of reactions triggered in response to pro-apoptotic signals, while the non-enzymatic function of MPO acts by protecting cancer cells from caspase-3-mediated cell apoptosis." (PMID 38275657, 2024). "Mice treated with MPO inhibitors could not form NETs and are always utilized to observe the impacts of NETs on cancer." (PMID 37188184, 2023). "Furthermore, the levels of plasma H3Cit, MPO, and DNA were significantly elevated in IS patients with cancer as compared to those without." (PMID 36224604, 2022). "Finally, MPO activity, protein and IL-10 were all altered in BAL fluid of cancer septic mice although this was not accompanied by differences in histologic lung inflammation or other BAL cytokines between previously healthy septic mice and cancer septic mice." (PMID 27018973, 2016). "Interestingly MPO and IL-17 positive TICI correlated significantly in all biopsies (rs = 0.42; p < 0.001), in biopsies of only primary (rs = 0.41; p = 0.004) and in biopsies of only recurrent carcinomas (rs = 0.40; p = 0.007)." (PMID 27531373, 2016). "However, serum myeloperoxidase concentration was not related to total mortality, respiratory mortality, or deaths from malignancies." (PMID 23637811, 2013). "However, this aspect of MPO functionality has not been investigated in the setting of cancer." (PMID 40797324, 2025). "Moreover, Choi and colleagues reported that açaí treatment down-regulated myeloperoxidase (MPO) and proinflammatory cytokines (TNF-α, IL-1β and IL-6), inhibited cyclooxygenase 2 (COX-2), PCNA and Bcl-2, and increased Bad and cleaved caspase-3 expression in an experimental model of cancer colon." (PMID 29966007, 2018). "This was not seen for cells expressing CD15+MPO− (CD15+; non-activated or immature neutrophils) (PFS CD15+; P = 0.493 and OS CD15+ TC; P = 0.463), or CD15+ expression in malignant tumor cells (CD15+ TC) (PFS CD15+ TC; P = 0.740 and OS CD15+ TC; P = 0.151)." (PMID 40652059, 2025). "Interestingly, although H3Cit was not increased in severely ill patients without known cancer compared to healthy individuals, MPO-DNA complexes were significantly elevated in these severely ill patients, and a positive correlation between H3Cit and MPO-DNA was observed." (PMID 29324871, 2018). "BMSCs collected from cancer primary sites or from bone marrow were epithelial marker (EPCAM), endothelial marker (CD31), hematopoietic marker (CD45 and CD34) and neutrophil marker (MPO) negative." (PMID 31819035, 2019).